IL6 (interleukin 6)
Diseases named in the same sentence as IL6 in open-access papers (continued):
Sharing a sentence is not in itself a finding about the gene and the disease.
vitiligo (continued). "In vitiligo affected skin, a significantly higher expression of TNF-α, IL-6, IFN-γ was detected compared with healthy controls and perilesional, non-lesional skin indicating that cytokine imbalance plays an important role in the depigmentation process of vitiligo." (PMID 23284977, 2012). "Thus, to verify if Ins and IGF-1 evoke a pro-inflammatory feature in vitiligo keratinocytes and the possible role in immunopathogenesis, we quantified the amount of several secreted interleukins that demonstrated increased quantities of CXCL10, IL-6, IL-8, IL-1α, IL1-β, and TNFα." (PMID 40277891, 2025). "Moreover, non-segmental vitiligo patients also presented increased levels of IL-6." (PMID 31505868, 2019). "Finally, we found that expression levels of IL-6 (0.27-fold) and IL-17 (0.30-fold), but not IL-10 or IFN-γ, were also decreased in T cells from patients with vitiligo (n = 6) compared with the controls (n = 6), after the transfection of plasmid encoding LOC100506314." (PMID 37731844, 2023).
gastritis (66 papers, 2013 to 2026). Inflammation of the stomach. "IL-6 is a pro-inflammatory cytokine that is central to the immune response to H. pylori infection, the most common cause of gastritis." (PMID 41376630, 2025). "IL-1β, IL-6, and IL-8 were lower in H. pylori infection-associated gastritis samples, whereas the levels of IL-12, IL-18, and TNF-α were higher." (PMID 38561502, 2024). "The high levels of cytokines release, like TNF-a (Tumor necrosis factor-a), IL-6 (interleukin-6), and IL-10 (interleukin-10) caused by aspirin ingestion are critical in the acute phase of inflammation and severity of gastritis." (PMID 37184667, 2023). "Helicobacter pylori (H. pylori), one of the causes of gastritis, induces inflammatory responses mediated by pro-inflammatory cytokines, such as IL6." (PMID 35336597, 2022). "Th1 cytokines like IL-6 promote chronic atrophic gastritis and predisposition to tumorigenesis through inhibition of gastrin and somatostatin." (PMID 32231118, 2020). "The gastric mucosal levels of IL-6 are elevated in H. pylori-associated gastritis and they decline after the infection is being treated." (PMID 32636937, 2020). "Furthermore, NO production is associated with interleukin-6 up regulation and inflammation in gastritis patients and a higher risk of GC." (PMID 39897791, 2025). "Importantly, the IL-6/STAT3 axis is also involved in the polarization of macrophages, which are believed to be mediators in H. pylori-associated gastritis, through release of IL-6." (PMID 38422751, 2024). "IL-6, a key proinflammatory cytokine, has been linked with the severity of inflammation and may serve as a biomarker for the progression of gastritis." (PMID 38561502, 2024). "In gastritis, IL-6 mainly affects the damage and repair process of gastric mucosa by activating the JAK/STAT3 signaling pathway, regulating inflammatory response and immune cell differentiation." (PMID 41376630, 2025). "Generally, cytokine levels were higher in gastritis, but in H. pylori-infected gastritis, IL-1β, IL-6, and IL-8 levels were lower compared to H. pylori-independent gastritis, while IL-12, IL-18, and TNF-α levels were higher." (PMID 38561502, 2024). "Our investigation delves into the differential expression of key cytokines in gastric tissue, including IL-1β, IL-6, IL-8, IL-12, IL-18, and TNF-α in the context of H. pylori-associated and H. pylori-independent gastritis." (PMID 38561502, 2024). "Key cytokines identified as playing a crucial role in the development and progression of gastritis include IL-1β, IL-6, IL-8, IL-12, IL-18, and TNF-α23–26." (PMID 38561502, 2024). "HP infection is correlated with local production of cytokines, of which, IL-6 is overexpressed at the margin of gastric ulcer in H. pylori-positive gastritis." (PMID 39497715, 2024). "Specifically, they observed lower expression levels of IL-6 in HP-positive patients compared to those with HP-negative gastritis." (PMID 39193325, 2024). "Among them, IL-6 activates the STAT3 pathway, of which the activation is correlated with the H. pylori-associated gastritis and gastric cancer." (PMID 35013458, 2022). "In summary, in this study, Mb-ME reduced the production of nitric oxide; decreased the mRNA expression of pro-inflammatory genes such as TNF-α, IL-6, and iNOS; and relieved acute gastritis symptoms triggered by HCl/EtOH treatment." (PMID 35270116, 2022). "IL-6 and IL-8 are considered key elements involved in the progression of gastritis because they have broad biological effects on mononuclear cells." (PMID 35506423, 2022). "Among which, interleukin- (IL-) 6 (IL-6) and CC-chemokine ligand 2 (CCL2), as members of 15 common genes, have been reported to be associated with the progression of gastritis." (PMID 34471638, 2021). "Lastly, when the mRNA expression levels in gastric tissue were measured in the acute gastritis model, we confirmed that the expression of IL-6 was decreased in the group injected orally with Pd-EE (100 mg/kg) and ranitidine (40 mg/kg)." (PMID 34684856, 2021).
gastritis (continued). "IL-6 is one of the important cytokines that mediate humoral immunity and plays a role in the pathogenesis of gastritis and MetS." (PMID 27851820, 2016). "As a result, macrophage-related inflammatory mediators, including IL-1β, VEGF, IL-6, and MMP-2, all known to be engaged in either H. pylori-associated gastritis or carcinogenesis, were significantly increased in Group II." (PMID 26317548, 2015). "Immunohistochemical analysis of IL-6 in human samples indicated that IL-6 was expressed in the stroma of some cases of gastritis and adenoma." (PMID 23593346, 2013). "In conclusion, IL-6 has an important dual role in the TME of gastritis and GC." (PMID 41376630, 2025). "In the future, it is expected that the treatment strategies for gastritis and GC will be optimized by precisely regulating the IL-6 signaling pathway, combined with immune checkpoint inhibitors or other treatments, and providing patients with more effective clinical interventions." (PMID 41376630, 2025). "Recent studies tend to suggest that the immunosuppressive and pro-inflammatory microenvironment created by chronic atrophic gastritis, characterized by the continuous high expression of cytokines such as IL-6 and TNF-α, may be a more upstream driving factor." (PMID 41333217, 2025). "Artemisia capillaris Thunb. from Asteraceae revealed remarkable early-stage anti-gastritis ability and anti-chronic gastritis and anti-precancerous lesion capacity by down-regulating IL-1β, IL-6, TNF-α, COX-2, PGE2, gastric F4/80 protein, and MDA with low p-p65 and pSTAT3 expression." (PMID 40264171, 2025). "Prolonged IL-6 signaling may lead to chronic inflammation that impairs mucosal healing and promotes progression of gastritis to pre-cancerous states such as atrophic gastritis or intestinal metaplasia." (PMID 41376630, 2025). "Interleukins 6 and 13 (IL-6 and IL-13) promote EBV proliferation, and elevated levels of pro-inflammatory cytokines such as IL-1β, tumor necrosis factor α (TNF-α), and IL-8 have been observed in EBV and H. pylori coinfection associated with severe gastritis." (PMID 40110195, 2025). "EPS54 also significantly alleviated the symptoms of gastritis in the H. pylori-infected mice by down-regulating the mRNA expression levels of pro-inflammatory cytokines IL-6, IL-8, IL-1β and TNF-α and up-regulating the mRNA expression of inflammatory cytokines IL-10 in gastric cells." (PMID 38978704, 2024). "Moreover, gastric mucosal levels of IL-6 are found to be higher in patients with H. pylori-positive gastritis and decrease following successful eradication of the infection." (PMID 38561502, 2024). "The activation of NF-κ B may in turn aggravate gastritis via the induction of proinflammatory cytokines such IL-1, IL-6, IL-8 and TNF-α." (PMID 36841844, 2023). "IL-6 is known to require NF-κB activation during H. pylori-related gastritis." (PMID 35565724, 2022). "Moreover, IL-6 has been reported to be involved in the treatment of gastritis by Atractylodes Macrocephala Koidz." (PMID 34471638, 2021). "In H. pylori-infected gastritis patients, IL-6 levels are significantly increased." (PMID 32636937, 2020). "Gastritis patients with high IL-6 levels may also benefit from IL-6 inhibition as a preventive measure against gastric carcinogenesis." (PMID 32231118, 2020). "The possible inflammatory markers that can be used to evaluate gastritis are the interleukin family—mainly IL-6—and other proinflammatory cytokines, namely the tumor necrosis factor alpha (TNF-α), IL-1, and IL-8, C-reactive protein (CRP), platelets and neutrophils." (PMID 32722268, 2020). "For example, increased production of pro-inflammatory cytokines in the mucus (such as IL-1, IL-6, IL-10, TNF-α, and interferon-γ) of those who are at risk of H. pylori infection is associated with gastritis induced by H. pylori and the severity of inflammation." (PMID 30320011, 2018). "Therefore, IL-6 plays a crucial role in the TME of gastritis and GC." (PMID 41376630, 2025).
gastritis (continued). "EPS54 could also effectively alleviate the gastritis in the H. pylori-infected mice by down-regulating the mRNA expression levels of pro-inflammatory cytokines IL-6, IL-8, IL-1β and TNF-α and up-regulating the mRNA expression of inflammatory cytokine IL-10 in gastric cells." (PMID 38978704, 2024). "This study demonstrates that SA-derived extracellular vesicles (SA-EVs) accumulate in gastric tissue, enter epithelial cells, and induce acute gastritis characterized by neutrophil infiltration and elevated cytokines (TNF-α, IL-6, IL-17A)." (PMID 41614638, 2026). "Neutral corn protein hydrolysate attenuated gastritis through reduction of MPO, IL-1β, IL-6, KC, TNF-α, and MCP-1." (PMID 40264171, 2025). "Our study provides invaluable insights into the inflammatory mechanisms involved by exploring key cytokines such as IL-1β, IL-6, IL-8, IL-12, IL-18, and TNF-α in gastritis." (PMID 38561502, 2024). "Studies have shown that TCM can reduce H. pylori-induced gastritis by decreasing the expression of IL-8, TNF-α, IL-6, iNOS, and IFN-γ." (PMID 38195483, 2024). "Commercially available ELISA plates were used to confirm further the influence of H. pylori infection on the expression of cytokines (IL-1β, IL-6, IL-8, IL-12, IL-18, and TNF-α) in gastritis." (PMID 38561502, 2024). "Experiments in the gastritis mouse model indicated that Pp-EE suppresses HCl/EtOH-induced gastric lesions, the expression levels of COX-2, IL-6, and TNF-α, and the phosphorylation of p65, p50, and Src." (PMID 35807703, 2022). "The study results showed that TNF-α, IL-1β, IL-6, TLR4, and MBL2 are common among Covid-19, IBD, gastritis, and diarrhea." (PMID 35845309, 2022). "In the mouse gastritis model, Gc-ME administration ameliorated stomach ulcers and reduced the expression of inflammatory genes (COX-2, IL-1β, IL6, and iNOS) and the phosphorylation of Src and IκBα." (PMID 36559672, 2022). "Our results indicate that heparanase promotes M1 polarization of macrophages driven by H. pylori or LPS + INF-γ, resulting in increased expression of pro-inflammatory cytokines such as IL-1β, IL-6 and TNF-α, and further aggravating the severity of gastritis." (PMID 34220822, 2021). "The verification results of the GSE5081 dataset displayed that IL-6 and CCL2 were significantly upregulated in gastritis compared to normal, which was consistent with the results in the GSE60427 dataset." (PMID 34471638, 2021). "We observed a significant dose-dependent decrease and increase in the levels of pro-inflammatory cytokine IL-6 and IFN-γ for DFMO-treated mice compared to untreated mice exhibiting gastritis and to H. pylori-eradicated mice (p < 0.0001), respectively." (PMID 32231118, 2020). "In H. pylori infection-associated gastritis, the IL-1β, IL-6, and IL-8 were lower, whereas IL-12, IL-18, and TNF-α were higher than those in gastritis without H. pylori infection." (PMID 38561502, 2024). "The IL-1β, IL-6, and IL-8 levels were lower in H. pylori-infected gastritis compared to non-infected gastritis." (PMID 38561502, 2024). "Although the levels of IL-5, IL-6, IL-9, IL-10, IL-13, and IL-21 were higher in patients with gastritis than Hp- group, this increase was not significant." (PMID 39807418, 2024). "Furthermore, individuals with Hp gastritis at high altitudes demonstrate elevated levels of serum TNF-α, IL-1β, IL-6, and MDA, as well as reduced serum SOD and GSH-Px activities." (PMID 38970131, 2024). "The results of the in vivo mouse acute gastritis model showed that ICE significantly reduced inflammatory lesions in the gastric mucosa and remarkably downregulated the expression of iNOS, TNF-α, IL-1β, and IL-6 mRNA in gastric tissue." (PMID 36386225, 2022).
gastritis (continued). "Pediatric patients with H. pylori gastritis showed significantly lower levels of serum ferritin, prohepcidin, and IL-6 compared to those with H. pylori-negative gastritis and the healthy control." (PMID 36555966, 2022). "To investigate whether naringenin could affect ethanol-induced gastritis, we examined the effects on the secretion of TNF-α, IL-6, and IL-8 expression in ethanol-stimulated KATO III cells." (PMID 34769415, 2021). "In addition, similar to phenotype of Cc-ME in gastritis model, increased mRNA levels of inflammatory genes (COX-2, IFN-β, IFN-γ, IL-1β, IL-6, iNOS, and TNF-α) were also significantly suppressed in both Cc-ME- and ranitidine-treated groups." (PMID 29725354, 2018). "None of gastric adenoma, gastritis, or healthy controls was positively stained for IL-6 in the epithelial cells." (PMID 23593346, 2013). "Apart from these genes, targets like CCL2, IL6, JAK2, IL2RA and CXCR1 were also of vital importance in the Hot herbs’ targets network, which might infer us that another potential mechanism of Hot herbs against Cold ZEHNG gastritis was to regulate immune responses." (PMID 39367502, 2024). "In parallel, H. pylori-administered mice demonstrated gastritis with inflammatory responses, as indicated by the prominent histological scores based on inflammatory cell infiltration and epithelial damage and increased inflammatory cytokines (IL-6 and TNF-α, but not IL-10) in the stomach." (PMID 35955701, 2022). "Focusing on Il-1β, IL-6, IL-8, IL-12, IL-18, and TNF-α, we analysed gene and protein levels to differentiate between H. pylori-infected and non-infected gastritis." (PMID 38561502, 2024). "In patients with non-ulcer dyspepsia, gastritis or peptic ulcers that were infected by H. pylori, a high secretion of IL-17, IFN-γ, IL-23, IL-6, IL-10, TNF-α, IL-21, IL-8, and IL-37 was reported." (PMID 35955936, 2022). "Patients with atrophic gastritis presented significant lower levels of IL-2, IL-9, IL-6, TGF-β, GM-CSF, IL-17 and ET-1 (p < 0.005) compared to patients without gastritis." (PMID 32947843, 2020). "Patients with atrophic gastritis showed significant lower levels of many cytokines (IL-2 (p = 0.036), IL-9 (p = 0.001), IL-6 (p = 0.038), and TGF-β (p = 0.015) GM-CSF (p = 0.001), IL-17 (p = 0.001) and ET-1 (p = 0.001)) compared to patients without gastritis." (PMID 32947843, 2020).
meningitis (66 papers, 1993 to 2025). A disorder characterized by acute inflammation of the meninges of the brain and/or spinal cord. "Several biomarkers (IL-6, S100, NSE, and 5HIAA) were studied in our research, and only one of them (IL-6) demonstrated potential diagnostic significance for the prognosis of post-neurosurgical meningitis." (PMID 35330399, 2022). "On univariate analysis and compared to meningitis patients infected with serotype 10A, those infected with 6D, 23A, 6A, 16F and 3 were associated with lower levels of IL-6 concentrations in the CSF." (PMID 34620928, 2021). "Low levels of IL-1β, TNF-α or IL-6 in nasopharyngeal secretions were observed in children with recurrent episodes of acute otitis media, an important cause of meningitis." (PMID 26316174, 2015). "Low levels of IL-1β, TNF-α and IL-6 in nasopharyngeal secretion were observed in children with recurrent episodes of acute otitis media, an important cause of meningitis." (PMID 21473761, 2011). "In a recent study of 16 diagnostic markers of meningitis, only granulocytes, lactate, IL-6 and IL-1β in CSF exhibited similar reliability." (PMID 17386119, 2007). "To determine whether the immune system is affected by PLG and induces meningitis symptoms, we investigated the expression levels of EV-A71-associated cytokines such as IL-1β, IL-6, MCP-1, IL-10, and IFN-γ in serum after EV-A71 infection." (PMID 40377310, 2025). "Finally, intraperitoneal injection of JEV into SMS1-deficient mice showed an obvious decrease of JEV infection and its associated pathologies, such as meningitis, lymphocyte infiltration, and elevation of interleukin 6, compared with wild type mice." (PMID 27892528, 2016). "High levels of TNF-α, IL-6 and IL-1β are characteristic of meningitis processes and may be associated with disease severity and the occurrence of sequelae." (PMID 21473761, 2011). "have also found inflammatory markers elevated in the CSF during VZV-related meningitis, including interferon gamma, interleukins IL-6, IL-8, IL-10, IL-17F, IL-1RA, chemokines CXCL-9, CXCL-10, CCL-2 and G-CSF." (PMID 40416981, 2025). "The serum of the PM mice also displayed significantly elevated levels of the inflammatory cytokines TNF‐α, IL‐6, and IL‐1β in serum and brain homogenates for the meningitis group." (PMID 39887961, 2025). "Only few IL-6 mRNA+ inflammatory cells were found in the areas of meningitis from some IP inoculated animals." (PMID 40125323, 2025). "A study with 121 patients found highly increased IL-6 levels within the CSF in patients with bacterial and viral meningitis during the acute phase of meningitis." (PMID 38678151, 2024). "C-reactive protein (CRP), tumor necrosisfactor-α (TNF-α), interleukin-1β (IL-1β), interleukin-6(IL-6), procalcitonin (PCT) are considered beingclosely implicated in the presence and progression ofpurulent meningitis." (PMID 39139150, 2024). "Recent studies have shown that, apart from anti-viral immunity and pathogen clearance functions, annexin 1 attenuates neutrophil migration and IL-6 expression through formyl peptide receptor 2 in a Streptococcus suis induced meningitis mouse model." (PMID 38907250, 2024). "The predictive value of CSF IL-6 in patients with an external ventricular drainage for the diagnosis of CNS infection prior to clinically manifesting meningitis was 2700 pg/mL." (PMID 35330399, 2022). "Patients with signs of post-neurosurgical meningitis manifested statistically significant higher median values of IL-6 (up to a 10-fold increase in median)." (PMID 35330399, 2022). "With a particular emphasis on the function of AnxA1 in the regulation of neutrophil recruitment and interleukin-6 (IL-6) production in S. suis-induced meningitis, we demonstrate an immunomodulatory role for AnxA1 in S. suis-induced infection through Fpr2." (PMID 33318141, 2021). "CSF IL-6 level is often elevated in meningitis patients, thus, it is reasonable that CSF IL-6 level is increased at acute phase and decreased along the remission." (PMID 28860590, 2017).